MSH6 (mutS homolog 6)
Diseases named in the same sentence as MSH6 in open-access papers (continued):
Sharing a sentence is not in itself a finding about the gene and the disease.
cancer (continued). "A cancer-derived mutation located between the two nuclear localization signals of human Msh6 resulted in a significant reduction in the localization of hMsh6 in the nucleus, suggesting that an altered protein localization pattern may contribute to cancer." (PMID 38139447, 2023). "Only in N0, DNA (excision-) repair (involved genes: CDKN1A, PPM1D, and DDB2) was predicted to be a downstream function, while molecular networks in N2+ were associated with cancer, as well as injury and abnormalities (among others, downregulation of MSH6, CCNE2, and CHUK)." (PMID 36068491, 2022). "On the other hand, cancers associated with the MSH6 protein may be missed during MSI testing because this gene is preferentially involved in repair of mononucleotide repeats and mononucleotide markers are not included in all MSI panels." (PMID 34998373, 2022). "A number of recent studies have also shown that the expression of MSH6 was associated with the poor survival of cancer patients such as LGG and SARC, and that MSH6 gene mutations may increase the risk of certain tumors with lower prevalence, such as ACC." (PMID 34941572, 2021). "Edelmann’s results revealed that mutations in the MSH6 gene increased cancer susceptibility and may be directly related to hereditary cancer predisposition syndrome and certain sporadic tumors without microsatellite instability." (PMID 34941572, 2021). "Additionally, the MSH6 pathogenic variant seems to be a gender-specific factor in cancer susceptibility with higher EC risk, but only a low risk of colon cancer in both sexes." (PMID 33430305, 2021). "Besides, MSH6 mutation carriers appear to be at low risk of cancer, probably because the isolated loss of MSH6 gene function does not completely abrogate MMR activity due to the overlapping functions of MSH3." (PMID 34201893, 2021). "Notably, female path_MSH6 carriers are at highest risk of endometrial cancer compared with cancer in other organs." (PMID 32708519, 2020). "Protein loss of MLH1/PMS2 was found in two and MSH6 loss in one cancer with MSI." (PMID 32144630, 2020). "Finally, the association of MSH6 rs1042821with DTC, observed in this study for female but not male individuals, is compatible with the growing evidence placing DTC as an oestrogen-associated cancer and implicating MSH6 in such cancers." (PMID 31374908, 2019). "The retrospective nature of our study and the paucity of individuals with pathogenic variants in PMS2 and MSH6 necessitated wide confidence intervals that may have led to an underestimation of cancer types in these two groups." (PMID 30386444, 2018). "Specifically, individuals with MSH6 mutations could be offered cancer surveillance from a later age." (PMID 28772289, 2017).
cancer (continued). "Based on these data, we envision that cancers triggered by EXO1 mutations may be nearly as common as those initiated by MSH6 mutations." (PMID 29069084, 2017). "Apart from the mutation in MSH6, two further mutations in genes known to be mutated in cancer, but rarely in biliary tract carcinoma (PTPRC, MSN), were identified as “mutations of unknown relevance”." (PMID 28146430, 2017). "Cancer surveillance could be started later for individuals with MSH6 mutations, and surveillance for EC could be started later in those with truncating MLH1 mutations." (PMID 28772289, 2017). "Among them, TACSTD1 and MSH6 have been associated with cancer in the literature." (PMID 26515818, 2016). "However, several studies showed association of other SNPs in MSH3 and MSH6 genes in different cancers." (PMID 23437280, 2013). "Similarly, the observed risk of dying from ovarian cancer in path_MSH6 or path_PMS2 carriers diagnosed before 50 years of age was 0%, and in these carriers, prophylactic oophorectomy before 50 years of age solely for cancer prevention reasons is considered unwarranted and unethical." (PMID 37821984, 2023). "Therefore, no direct link could be made between the MSH6 c.3936_4001+8dup (intronic) variant and MSH6-deficiency in any cancer or preneoplasm." (PMID 36612224, 2022). "However, some of our observed mutations have not been linked to dMMR CRCs yet and we could detect up to six synchronous MMR/HRR mutations in our MLH1-/PMS2-/MSH6- cases, which is something we rarely observe in clinical practice in other cancer entities." (PMID 36387226, 2022). "While one patient with HPV‐negative cancer carried a pathogenic MMR gene variant (in MSH6), the HDR germline variants were found in patients with HPV‐positive cancers and tended to associate with HPV18." (PMID 39440754, 2025). "Combined loss of MSH6 and PMS2 (MSI-H) was found in 30% of cases, particularly in poorly differentiated tumors, T3 stage tumors, stage II and III cancers, and node-positive groups." (PMID 41907888, 2025).
cancer (continued). "Immunohistochemical staining of the diagnostic biopsy had shown a MMRd phenotype with a loss of MSH6 protein expression both in the IPMN component and in the carcinoma cells." (PMID 41120797, 2025). "Only in the exploratory analysis, a positive MSH6 result was found to be close to significantly different in SD vs FIT-IC cancers (p= 0.08)." (PMID 39286015, 2024). "Two suspected LS patients with first cancer diagnosis aged 27 or 38 years were found to be homozygous for an MMR (likely) pathogenic variant, MSH6 c.3226C>T (p.(Arg1076Cys)), or variant of uncertain significance (VUS), MLH1 c.306G>A (p.(Glu102=))." (PMID 38789506, 2024). "Curiously, the MMR genes MutS homolog 6 (MSH6) and MutS homolog 3 (MSH3) also contain coding homopolymers, and these are frequent mutational targets in MMR-deficient cancers." (PMID 38956208, 2024). "All these variants are present in heterozygosity, and many of them occurred in tumor suppressor genes and transcription factors that have a role in cancer development and T cell function, like MSH6, ARID1A, CARD11, CBL and SRC30–33." (PMID 38688902, 2024).
cancer (continued). "Comparison of msh6 expression in healthy individuals and cancer patients presented a significant elevation in msh6 expression in the cancer group compared to the control one (P value = 0.0001)." (PMID 38395750, 2024). "Differences in lifetime risk of CRC are known, showing that carriers of pathogenic variants in MSH6 and PMS2 have a lower risk of developing cancer, especially CRC and at later ages of onset than those with variants in MLH1 and MSH24–12." (PMID 37914736, 2023). "A recent integrative pan-cancer analysis suggested that MSH6 expression is correlated with a poor prognosis, including in ACC." (PMID 37296718, 2023). "For example, there were 13 subjects with MSH6 c.733A>T, which is considered a VUS, all of whom had cancer or were high-risk subjects." (PMID 37306523, 2023). "Here, our results also revealed that the VUS of MSH6 and POLQ suggested potentially different trends in association with cancer in women and men, respectively." (PMID 36896836, 2023).
cancer (continued). "Well‐known cancer critical genes like BRCA1, IDH1, ERG, KMT2C, MSH6 and PALB2 were among the mutated genes in the metastatic samples." (PMID 35880692, 2023). "MLH1-/PMS2-/MSH6- cancer cases almost arose throughout the entire digestive tract: from the gastric antrum to the left colic flexur." (PMID 36387226, 2022). "We also identified medically actionable variants in eight other cancer-related SFs genes, including APC, MAX, MSH6, MLH1, PALB2, PMS2, SDHB, and TSC2." (PMID 36143288, 2022). "Promoter hypermethylation and mutational silencing of HR and MMR genes, such as RB, BRCA1/2, PTEN, MLH1, MSH3, MSH6 have been identified in human cancer." (PMID 36076047, 2022). "Two of these 20 patients were also found to have pathogenic variants in a second cancer predisposition gene, CHEK2 in one patient, and MSH6 in the other (patient ID: 6 and 235 respectively)." (PMID 35710434, 2022). "The mother’s pedigree was constructed based on data provided by the proposita to determine if there was a history of cancer consistent with MSH6-LS." (PMID 36612224, 2022). "In total, 17 (94%) of the variants were private to a single person and were mostly related to cancer predisposition genes such as MUTYH, MSH6, BRCA2, and PALB2." (PMID 35562925, 2022).